IL1B (interleukin 1 beta)
Diseases named in the same sentence as IL1B in open-access papers (continued):
Sharing a sentence is not in itself a finding about the gene and the disease.
Sepsis (continued). "Accordingly, in contrast with inflammatory cytokines such as IL-1β, IL-6, TNF-α, and IFN-γ, elevation of IL-18 has levels been reported to be characteristic of AOSD and, thus, potentially useful for differentiating AOSD from sepsis." (PMID 32381117, 2020). "IL-1β and IFN-γ were 15~20 pg/ml and 4~6 pg/ml at 24 h and 48 h in the early stage of CLP but significantly increased to 20~40 pg/ml and 10-20 pg/ml in the late sepsis." (PMID 32774145, 2020). "In this study, we found disordered jejunal tissue structure in the sepsis model group, with decreased length of intestinal villi, reduced V/C values, reduced thickness of the mucosal layer, and increased levels of serum TNF-α and IL-1β." (PMID 33200654, 2020). "Our findings were consistent with other neonatal studies that found IL-1β concentrations were not different during sepsis." (PMID 32479514, 2020). "Delivery of NaHS to sepsis-induced mice leads to a marked increase in lung pro-inflammatory cytokines TNF-α, IL-1β, IL-6, chemokines MIP-1α and MIP-2, and adhesion molecules P-selectin, E-selectin, VCAM-1, and ICAM-1 which affect inflammation and immune cell migration." (PMID 33330130, 2020). "It was found that proinflammatory cytokines, including IL-1β, IL-6, and TNF-α, substantially decreased after EVs were applied to LPS-stimulated macrophages and mice, and thus, LPS induced M1 polarization was inhibited and sepsis was strongly alleviated." (PMID 32719678, 2020). "In our sepsis model, the injurious pulmonary inflammatory response is closely related to high levels of inflammatory mediators (TNF-α, IL-1β, and IL-6) found in the septic mesenteric lymph, especially with respect to the effect of the amplified inflammatory cascade response seen in septic syndrome." (PMID 33145344, 2020). "This has also been shown with anakinra, an IL-1β decoy receptor, which failed to conclusively show a survival benefit for patients with sepsis or septic shock." (PMID 32849612, 2020). "IL-6, IL-1β and TNF-α are among the major cytokines responsible for sepsis disease pathogenesis." (PMID 32117233, 2020). "Our findings imply that STAT3 is critical for the production of different pro-inflammatory mediators, including TNF-α, IL-1β, IL-6, and MCP-1, in CLP-induced sepsis, although STAT3 would work coordinately with other transcriptional co-activators or transcription factors." (PMID 32943679, 2020). "Simvastatin treatment was able to reduce the levels of TNF-α, IL-6, MIF, and IL-1β 24 hours after sepsis induction, indicating an important negative immunomodulary effect of simvastatin in this model." (PMID 33110395, 2020). "In the sepsis patients, the serum levels of the proinflammatory cytokines IL-6, IL-8, MCP-1, and IL-10 were strikingly higher than those in healthy controls, and the serum levels of IL-1β were slightly elevated." (PMID 32826331, 2020). "The levels of serum TNF-α, IL-1β, and IL-6 were increased significantly in rats in the sepsis group compared to rats in the sham group 24 h after surgery (P < 0.01), while TNF-α, IL-1β, and IL-6 concentrations at 24 h after CLP were reduced after NRG-1β treatment (P < 0.01)." (PMID 32765805, 2020). "Moreover, the protective effect of PD against the sepsis-induced increase in serum cytokines, including TNF-α, IL-1β, and IL-6, was inhibited by mdivi-1 treatment." (PMID 32131850, 2020). "For many years it was thought that sepsis embodies an uncontrolled pro-inflammatory response driven by the production of pro-inflammatory cytokines such as tumor necrosis factor (TNF)-α and interleukin (IL)-1β in the first hours after infection." (PMID 32477337, 2020). "In addition, it has been reported that NETs promote peritoneal macrophage pyroptosis, a caspase-1-dependent regulated cell death, and the production of macrophage-derived Il-1β and TNF-α32 in sepsis." (PMID 33214582, 2020).
Sepsis (continued). "In Muc2−/− littermates following LPS challenge, mortality was associated with high circulatory signature sepsis pro-inflammatory cytokines TNF-α, IFN-γ, and IL-1β as early as 3 h that failed to resolve after 24 h." (PMID 31980623, 2020). "Also, circC3P1 dramatically attenuated pulmonary injury, decreased pro‐inflammatory cytokines (TNF‐a, IL‐6 and IL‐1β), cell apoptosis and p‐AKT/AKT levels induced by sepsis." (PMID 32846020, 2020). "IL-1β and IL-18, the downstream cytokines secreted upon inflammasome activation, were determined in serum samples to further confirm the role of ASC-speck+ leukocytes in sepsis patients." (PMID 33613537, 2020). "An in vivo study involving an LPS-stimulated mouse model of sepsis reported reduced levels of inflammatory mediators (TNF-α, IL-1β, and IL-6) and an elevated level of the anti-inflammatory cytokine IL-10 in septic mice fed with lyophilized powder of wild bitter gourd-supplemented diet." (PMID 33193799, 2020). "Although first discovered to play a role in the pathogenesis of sepsis, therapies to directly block TNF-α and IL-1β signaling have done more to change the progression and day-to-day symptomatology for patients with a variety of autoimmune and dermatological conditions." (PMID 32849612, 2020). "The in vitro models of sepsis were successfully established via stimulating HUVEC and macrophages by LPS for 24 hours, which showed pyroptosis of HUVECs and macrophages with the release of proinflammatory factors IL-1β and IL-18." (PMID 32851082, 2020). "In our study, we showed that the hippocampal expressions of IL-1β and IL-6 but not other inflammatory factors were upregulated by sepsis, suggesting IL-1β and IL-6 are specifically affected by CLP." (PMID 33061831, 2020). "Similarly, in the cecal ligation and puncture (CLP) sepsis model, PAG treatment reduced mRNA and protein levels of pro-inflammatory cytokines IL-1β, IL-6, TNF-α in mice, indicating that H2S potentiates systemic inflammation in sepsis." (PMID 33330130, 2020). "When changes in mRNAs of pro-inflammatory cytokines in lung, liver, and kidney tissues were investigated using real-time PCR, the greatly increased mRNA expression levels of TNF-α, IL-1β, and MCP-1 at 18 h after CLP-induced sepsis were significantly suppressed by stattic administration." (PMID 32943679, 2020). "Previous studies have clearly indicated the importance of IL-1β, IL-6, IL-10, and TNF-α in sepsis." (PMID 33324396, 2020). "To explore whether MRS could affect the NLRP3 inflammasome signaling pathway to improve sepsis injury, we measured the expression levels of p-P65, P65, pro-caspase-1, pro-IL-1β and NLRP3/caspase-1/IL-1β by Western blotting 12 and 24 h after CLP." (PMID 30779706, 2019). "This concomitant variation in levels of IL-10 and IL-1β was observed before in the experimental model of sepsis, in which the lack of C5 resulted in lower levels of both cytokines." (PMID 31687410, 2019). "Besides systemic lupus erythematosus, several acute systemic inflammatory diseases like systemic inflammatory response syndrome and sepsis show altered plasma levels of both HGF and IL-1β." (PMID 31068815, 2019). "In this study, the results showed that knockdown of miRNA-106a reduced LPS-induced the levels of inflammatory factor TNF-α, IL-1β and IL-6, suggesting that inhibiting the expression of miRNA-106a might inhibit the occurrence of AKI induced by sepsis." (PMID 31432993, 2019). "For example, it has been reported that treatment with bicuculline methiodide, a form of the GABAA receptor blocker that does not cross the blood–brain barrier, decreases IL-1β in blood in a rat model of sepsis." (PMID 30858801, 2019). "Interestingly, only Olv and Omg decreased the sepsis-induced secretion of the inflammatory cytokines, TNF-α, IL-6, and IL-1β and stimulated the secretion of the anti-inflammatory cytokine, IL-10." (PMID 31333903, 2019).
Sepsis (continued). "Exogenous IL-1β was effective in CD4 T-cell expansion in a dose-dependent manner, implying that this cytokine, released from MLN DCs during sepsis, may play a role, at least partly, in promoting septic inflammation." (PMID 31323786, 2019). "The disruption of TLR signaling pathway induced by live virulent E. coli and E. coli-derived LPS in pigs by CD14 neutralization antibodies resulted in decreased levels of pro-inflammatory cytokines IL-1β, IL-6, IL-8, and TNF-α, and lower granulocyte activation in a pig model of sepsis." (PMID 31847111, 2019). "In this study, we showed that GSKJ4 protects mice against septic death and reduces the expression of inflammatory factors IL-1β, TNF-α, IL-6, and MCP-1 in vivo, suggesting that JMJD3 may be the key molecule driving early sepsis progression." (PMID 30337925, 2018). "H9C2 cells were treated with LPS to induce sepsis, and miR-146a overexpression significantly increased the cell viability, reduced the apoptosis and ROS level, and attenuated the release of proinflammatory cytokines including TNF-α and IL-1β." (PMID 30224945, 2018). "Inflammatory cytokines, such as IL-1β, TNF-α, and IFN-γ, are detected in the blood of patients with sepsis and induce septic shock-like conditions when animals are administrated with these inflammatory cytokines, suggesting that these cytokines have key pathogenic roles in sepsis." (PMID 29928698, 2018). "Additionally, AA attenuated LPS-induced production of cytokines, such as iNOS, IL-1β and IL-6 in RAW264.7 macrophage cells and mice with experimental sepsis." (PMID 29599924, 2018). "However, we noticed significant decreases in the expression of pro-inflammatory cytokines IL-6 and IL-1β and chemokine MIP-2 in the lungs of B-1a cell-treated mice during sepsis." (PMID 30134811, 2018). "In early sepsis, JMJD3 contributes to the production of pro-inflammatory IL-1β." (PMID 30337925, 2018). "Previous studies suggested that TNF-α and IL-1β are involved in the initiation and regulation of inflammatory response; the application of murine monoclonal anti-TNF antibodies induced a transient improvement in ventricular function in patients with sepsis." (PMID 30224945, 2018). "IL-6 governs the production of acute phase proteins, and together with IL-1β, IL-12/23/p40, and TNF-α, are termed proinflammatory cytokines and are induced in intestinal mucosa during sepsis, and in enterocytes after in vitro treatment with endotoxin and other proinflammatory cytokines." (PMID 29491864, 2018). "TNF-α, Il-1β, and IL-6 are not considered to be “gold standard” biomarkers of sepsis due to their short half-life." (PMID 28367457, 2017). "In contrast, higher day 1 levels of TNF-α, IL-6, IL-8, and CRP (p = 0.013, p < 0.001, p = 0.001, and p = 0.017, respectively), but not IL-1β (p = 0.057), were observed in patients with septic shock compared with those with severe sepsis." (PMID 28542440, 2017). "Both male and female mice treated with either anti-IL-1α or anti-IL-1β alone as well as controls treated with unreactive IgG did not develop abscesses or sepsis." (PMID 28358036, 2017). "During sepsis, pro‐inflammatory cytokines such as tumour necrosis factor (TNF)‐α, interleukin (IL)‐1β, IL‐6 and IL‐17 and bacterial products could up‐regulate the level of G‐CSF which promotes both the generation of both mature and immature neutrophils." (PMID 28244690, 2017). "The injection of rSj-Cys significantly reduced the production of inflammatory cytokines including TNF-α, IL-6 and IL-1β compared to mice with sepsis without treatment." (PMID 28482922, 2017). "There was no statistical significance on the levels of IL-1β, IL-6, IL-2sR and IL-10 in sepsis-non AKI group compared with the control." (PMID 28296904, 2017).
Sepsis (continued). "In summary, our data demonstrated that IRE1-NF-κB pathway was obviously activated by ER stress during sepsis and contributed to the septic AKI through enhancing the production of pro-inflammatory cytokines (TNF-α, IL-1β and IL-6) in the renal proximal tubular epithelial cells." (PMID 28430592, 2017). "Interestingly, in a murine model of polymicrobial sepsis, inhibition of the PI3K pathway increased serum IL1-β, IL-6 and TNF-α levels and decreased the survival rate of septic mice." (PMID 28545453, 2017). "The present study demonstrates that GIK protects intestinal mucosal barrier function in CLP-induced sepsis and that UCP2 and the NLRP3/caspase-1/IL-1β signaling pathway may be involved in this process." (PMID 28428961, 2017). "Indeed, TNF-α, IL-1β, IL-6 mRNA expressions in the kidney were found to be greatly enhanced at 6 hours after CLP which was regarded as the early stage of sepsis." (PMID 28430592, 2017). "In patients with septic AKI, the levels of TNF-α, IL-1β, IL-6, IL-2sR and IL-10 were significantly increased, while the levels of IL-8 was significantly decreased compared with sepsis patients without AKI." (PMID 28296904, 2017). "Aberrant upregulation and activation of pro-inflammatory cytokines and chemokines, including TNF-α, IL-1β, IL-6, IL-8, CCL5, and CXCL8, has been correlated with the progression of chronic inflammatory diseases, such as tumor, sepsis, rheumatoid arthritis, psoriasis, and cytotoxicity." (PMID 29045468, 2017). "In contrast, in case of a clinically documented sepsis, intra-articular IL-1β concentrations were not elevated." (PMID 27688601, 2016). "On the other hand, type 1 diabetic mice lacking 5-LOX or the receptor for LTB4 produced less IL-1β, survived polymicrobial sepsis, and had decreased bacterial counts." (PMID 27887602, 2016). "In addition, IL-6, IL-1β, and TNF-α had a central role in activating cytokine cascade response in sepsis and partly involved in pathogenesis of MOF." (PMID 28042205, 2016). "Similarly, we found higher levels of the pro-inflammatory cytokine IL-1β in the EBC of patients with altered gas exchange and lower levels of the anti-inflammatory cytokine IL-10 in the EBC of patients with severe sepsis and severe CAP." (PMID 28702287, 2016). "The activities of complexes I and II of the mitochondrial respiratory chain are diminished in hearts from animals with sepsis, and this might be due to the detrimental effects of sepsis mediators such as NO, TNF-α, IL-1β, and others." (PMID 27011791, 2016). "In addition, H1R−/−/H2R−/− mice exhibited lower levels of IL-1β, IL-6, and MCP-1 mRNAs in lung, liver, and kidney tissues as compared with WT following sepsis." (PMID 27822777, 2016). "Here the authors show this switch drives IL-1β, IL-18 and HMGB1 release from macrophages by activating the NLRP3 and AIM2 inflammasomes via protein kinase R phosphorylation, a pathway that can be inhibited to prevent sepsis in mice." (PMID 27779186, 2016). "Among the three patient subgroups, the severe sepsis patients displayed the highest CX3CL1 expression level, whereas the sepsis subtype patients displayed the lowest expression of TNF-a, IL-6 and IL-1β." (PMID 25888255, 2015). "Therefore, we investigated blood IL-1β, IL-6, IL-4, IL-5, IL-10 and IFN-γ, which play important roles in sepsis." (PMID 26586517, 2015). "Increased values for IL-1β, IL-6, IL-10 and CXCL-2 were also observed in all volatile anesthetic sepsis groups compared to isoflurane-sham animals (all P <0.03), and IFN-γ was increased in isoflurane + CLP compared to isoflurane-sham animals (134.2 ± 131.9 versus 12.4 ± 12.2 pg/ml, P = 0.04)." (PMID 25887642, 2015). "This retrospective investigation analyzed the role of the cytokines IL1-β, sIL-2R, IL-6, IL-8, IL-10 and TNF-α as potential markers for major post-transplant adverse events including VOD, skin and intestinal GvHD, sepsis as well as bacterial, viral and fungal infections in 61 pediatric patients." (PMID 26315105, 2015).
Sepsis (continued). "In the context of sepsis, TNF-α, IL-1β, IL-6, and IL-8 are the most frequently altered cytokines." (PMID 24795771, 2014). "In conclusion, our findings show that an acute dose of 2 mg/kg leptin fails to influence HPA function or IL1β secretion, 4 h after injection, in a rat model of acute 25 μg/kg LPS-induced sepsis." (PMID 24578293, 2014). "Previous studies from our laboratory have demonstrated that caspase-1 does induce apoptosis during murine models of sepsis and that the apoptotic function is independent of its IL-1β and IL-18 processing function." (PMID 24643116, 2014). "Our findings suggest that leptin does not influence HPA function or IL1β secretion in a rat model of LPS-induced sepsis, and thus that leptin is unlikely to be involved in the acute-phase endocrine response to bacterial infection in rats." (PMID 24578293, 2014). "In mice with a conditional deletion of Atg7 in the intestinal epithelium, LPS induces higher levels of IL-1β mRNA, compared to wild type controls, while LC3B−/− mice produce higher levels of IL-1β and IL-18 in response to LPS- or cecal ligation and puncture (CLP)-induced sepsis." (PMID 23577011, 2013). "Moreover, our experiments and other studies demonstrated that neutrophils were a major subset to produce IL-1β and IL-10 and highly expressed NOD2 during CLP-induced sepsis." (PMID 23675299, 2013). "Furthermore, we found that NOD2-mediated IL-10 production by neutrophils enhanced C5a generation by suppressing CD55 expression on neutrophils in IL-1β-dependent and/or IL-1β-independent manners, thereby aggravating CLP-induced sepsis." (PMID 23675299, 2013). "Furthermore, NOD2-mediated IL-1β and IL-10 production also suppressed LPS-mediated cytokine production by peritoneal immune cells during CLP-induced sepsis." (PMID 23675299, 2013). "A detectable level of these markers was more common in patients with sepsis than patients with non-infective SIRS: IL1β 61% vs 15%, GMCSF 26% vs 1% and TNFα 3% vs 0%." (PMID 23531337, 2013). "Consistent with this suggestion, time points of recombinant IL-1β injection was critical to exert harmful effects on sepsis in Nod2−/− mice (data not shown)." (PMID 23675299, 2013). "Sepsis, a life-threatening disease with a high mortality rate, is accompanied by systemic inflammation with excessive production of pro-inflammatory cytokines including tumor necrosis factor-α (TNF-α) and interleukin-1β (IL-1β)." (PMID 24260470, 2013). "In clinical trials targeting proinflammatory cytokines, such as TNF-α or IL-1β, in patients with sepsis have not yielded the desirable outcomes." (PMID 23533310, 2013). "Release of cytokines (IL1β, IL-6, and TNFα), nitric oxide, endotoxins, and activation of caspases (caspases 3) in setting of a gram negative bacteremia and sepsis leading to myocardial depression and ventricular dilatation is another theory to explain SRTE." (PMID 23691359, 2013). "No significant changes were observed in IL-1β, IL-2, IL-4, IL-13, GM-CSF, FGFbasic or GM-CSF in caPI3K Tg mice in the presence or absence of sepsis (data not shown)." (PMID 23028587, 2012). "The results obtained strongly suggest that high levels of circulating TPO in patients with sepsis may favor the occurrence of myocardial depression in cooperation with TNF-α and IL-1β." (PMID 22577249, 2012). "Stimulation with MSU in the presence of LPS resulted in release of IL-1β from PBMCs isolated from healthy controls, but not from PBMCs of patients with sepsis." (PMID 21244670, 2011). "However, serial responses of IL-1β, TNF-α and IL-6 from PBMCs still need to be elucidated in patients with severe sepsis." (PMID 21939530, 2011). "It was found that many substances that act as mediators, which are elevated in sepsis and septic shock, such as tumor necrosis factor (TNF-α), interleukin (IL-1β), and a factor called complement anaphylatoxin (C5a), also have cardiodepressant properties in vitro." (PMID 22758615, 2011).